PFKFB3 (6-phosphofructo-2-kinase/fructose-2,6-biphosphatase 3)
Diseases named in the same sentence as PFKFB3 in open-access papers (continued):
Sharing a sentence is not in itself a finding about the gene and the disease.
breast tumor (2 papers, 2019 to 2025). "Nuclear protein levels of PFKFB3 were assessed with immunohistochemistry in primary breast tumors (n = 970) and whole-cell RNA levels with microarray gene expression (n = 765)." (PMID 40022029, 2025). "The primary aim of this study was to assess PFKFB3 protein and RNA levels in relation to reduced incidence of ipsilateral breast tumor recurrence (IBTR) after adjuvant radiotherapy." (PMID 40022029, 2025). "Given these limitations, we nevertheless found that 94% (46/49) of breast tumors that exhibited high Pfkfb3 expression (i.e., 3+ staining intensity) also displayed low levels of autophagy." (PMID 31413316, 2019). "Multivariable competing risks regression analysis was employed for the effect of radiotherapy on incidence of ipsilateral breast tumor recurrence (IBTR), depending on PFKFB3 levels." (PMID 40022029, 2025).
colorectal tumors (2 papers, 2023 to 2025). "There are no studies exploring the biological role of PFKFB3 in canine colorectal tumors, nor even a single paper on canine topics, which is a good direction for future exploration." (PMID 38098990, 2023).
endometriosis (2 papers, 2013 to 2021). The growth of functional endometrial tissue in anatomic sites outside the uterine body. "Our data show that HSF1 promotes endometriosis development, and enhances glycolysis via up-regulating PFKFB3 in endometriosis cells." (PMID 34107992, 2021). "Taken together, our findings provide some new insights into the functions of HSF1/PFKFB3 axis in endometriosis development, which is as a new target to treat endometriosis." (PMID 34107992, 2021). "In our study, we find PFKFB3 is highly expressed and promotes glycolysis in endometriosis cells, which is consistent with previous study that glycolysis promotes endometriosis development." (PMID 34107992, 2021). "Taken together, our results indicate that HSF1 promotes PFKFB3 expression in endometriosis cells." (PMID 34107992, 2021). "Interestingly, HSF1 enhanced glycolysis via up-regulating PFKFB3 expression in endometriosis cells, which was a key glycolysis enzyme." (PMID 34107992, 2021). "Our data demonstrated that HSF1 promoted endometriosis development via enhancing PFKFB3 expression." (PMID 34107992, 2021). "However, the role of PFKFB3 in endometriosis remains unclear." (PMID 34107992, 2021). "Although PFKFB3 has been shown to be expressed in human placenta, whether deregulation of this regulatory kinase can lead to proliferative disorders of the endometrium such as endometriosis, hyperplasia, or cancer constitutes an important question for future investigation." (PMID 24204309, 2013).
endothelial dysfunction (2 papers, 2023 to 2025). In vascular diseases, endothelial dysfunction is a systemic pathological state of the endothelium (the inner lining of blood vessels) and can be broadly defined as an imbalance between vasodilating and vasoconstricting substances produced by (or acting on) the endothelium. "We further show that the upregulation of PFKFB3 is a hallmark of T2D in both micro- and macrovascular ECs, and we identify the signaling mechanisms upstream of eNOS by which glycolysis promotes endothelial dysfunction." (PMID 40002359, 2025). "To further investigate the mechanisms by which PFKFB3 contributes to endothelial dysfunction and decreased NO bioavailability, we transduced HAECs with NOX1 adenovirus (in addition to its coactivators NOXA1 and NOXO1) and either GFP (control) or wt-, cyt-, or KD-PFKFB3." (PMID 40002359, 2025). "Furthermore, PFKFB3 enhanced the activities of NOX1 and NOX5, which are major contributors to endothelial dysfunction." (PMID 40002359, 2025). "However, to the best of our knowledge, no previous study has reported PFKFB3 gene and protein upregulation in the context of endothelial dysfunction in ECs related to T2D." (PMID 40002359, 2025).
endotoxemia (2 papers, 2021 to 2023). "In 2021, Xu and colleagues revealed that a deficiency in myeloid Pfkfb3 protects mice from lung edema and cardiac dysfunction in LPS-induced endotoxemia." (PMID 37199341, 2023). "Here, we identified a crucial role of myeloid 6-phosphofructo-2-kinase/fructose-2,6-bisphosphatase 3 (Pfkfb3), a glycolytic activator in lipopolysaccharide (LPS)-induced endotoxemia in mice." (PMID 34660743, 2021). "Furthermore, ablation of the endothelial Pfkfb3 gene protects mice from acute lung injury in LPS-induced endotoxemia." (PMID 37199341, 2023).
Fanconi anemia (2 papers, 2021 to 2025). Fanconi anemia (FA) is a hereditary DNA repair disorder characterized by progressive pancytopenia with bone marrow failure, variable congenital malformations and predisposition to develop hematological or solid tumors. "Other significant clusters were involved in membrane trafficking (Cluster 2), the Fanconi anemia DNA repair pathway (Cluster 5), and glycolysis regulation via PFKFB3 (Cluster 6)." (PMID 41226340, 2025). "Mechanistically, PFKFB3 promotes tolerance to and the repair of platinum-induced DNA interstrand crosslinks (ICLs) through modulation of the Fanconi anemia (FA) DNA repair pathway." (PMID 34298817, 2021).
gastric tumors (2 papers, 2019 to 2022). "To further verify the results, we also conducted differential expression analysis of PFKFB3 on the subtypes of gastric tumors based on TCGA." (PMID 35094634, 2022). "Then we performed the correlation analysis of PFKFB3 expression and clinical stages in subtypes of gastric tumors based on TCGA." (PMID 35094634, 2022).
gastric ulcer (2 papers, 2019 to 2024). An ulcerated lesion in the mucosal surface of the stomach. "Other authors suggest that andrographolide contributes, at least partially, to preserving gastric vascular homeostasis by inhibiting the PFKFB3-mediated glycolysis pathway during gastric ulcer development." (PMID 38540033, 2024). "In summary, this study demonstrates a protective function of andrographolide during gastric ulcer development, and identifies a novel mechanism via endothelial glycolysis pathway regulated by PFKFB3 to maintain gastric vascular homeostasis." (PMID 30899067, 2019). "Similarly, PFKFB3 expression further confirmed using IHC staining on gastric slide from ethanol induced gastric ulcer model." (PMID 30899067, 2019).
Impaired glucose tolerance (2 papers, 2024 to 2025). An abnormal resistance to glucose, i.e., a reduction in the ability to maintain glucose levels in the blood stream within normal limits following oral or intravenous administration of glucose. "Knockdown of PFKFB3 or pharmacological inhibition of glycolysis resulted in decreased insulin secretion and impaired glucose tolerance." (PMID 40600018, 2025).
infantile hemangioma (2 papers, 2023 to 2025). "Our previous research revealed that blocking glycolysis by targeting PFKFB3 can suppress the progression of infantile hemangioma, suggesting that PFKFB3 may promote the occurrence and development of IH by enhancing angiogenesis." (PMID 40438141, 2025).
inflammatory bowel disease (2 papers, 2022 to 2024). A spectrum of small and large bowel inflammatory diseases of unknown etiology. "A microarray analysis of inflammatory bowel disease (IBD) patient-derived fibroblasts revealed the elevated expression of PFKFB3 in inflamed versus non-inflamed tissues from IBD patients." (PMID 38542934, 2024).
influenza (2 papers, 2025). An acute viral infection of the respiratory tract, occurring in isolated cases, in epidemics, or in pandemics; it is caused by serologically different strains of viruses (influenzaviruses) designated A, B, and C, has a 3-day incubation period, and usually lasts for 3 to 10 days. "Similarly, inhibition of PFKFB3 has shown potential in reducing viral replication and inflammatory responses in preclinical models of influenza." (PMID 40723899, 2025). "In addition, although the compound 3-(3-pyridinyl)-1-(4-pyridinyl)-2-propen-1-one (3PO) has also been reported to attenuate influenza-related inflammation, its specificity as a PFKFB3 inhibitor is debated, suggesting that its observed effects may involve off-target mechanisms." (PMID 40723899, 2025). "Mechanistic highlights are provided for both the Warburg effect, where glycolysis shifts to lactate production during influenza infection, and the PFK1/PFKFB3 enzyme complex as the rate-determining regulator of glycolysis whose activity increases during the course of influenza infection." (PMID 41511331, 2025).
ischemia (2 papers, 2021 to 2025). A hypoperfusion of the BLOOD through an organ or tissue caused by a PATHOLOGIC CONSTRICTION or obstruction of its BLOOD VESSELS, or an absence of BLOOD CIRCULATION. "They found that endothelial PFKFB3 is required for ischemia-induced muscle revascularization and regeneration and that knocking PFKFB3 in muscle ECs impairs muscle function upon ischemia." (PMID 34485288, 2021). "In summary, we hypothesize that XFZYC acts by modulating glycolytic metabolism in endothelial cells, with a primary focus on regulating the critical target PFKFB3, thereby alleviating ischemia-related symptoms in PAD." (PMID 41471391, 2025).
keloid (2 papers, 2021 to 2024). An irregularly shaped, elevated mark on the skin caused by deposits of excessive amounts of collagen during wound healing. "Our findings indicated that SPARC could activate p38γ pathway to stabilize the expression of PFKFB3, and thus promote the glycolysis of KFs and the progression of keloid." (PMID 39482755, 2024). "Collectively, we speculated that SPARC might regulate the p38γ pathway to stabilize the expression of PFKFB3, and thus participated in the glycolysis process of KFs and the progression of keloid." (PMID 39482755, 2024). "In conclusion, our work demonstrated that SPARC could activate the p38γ pathway to stabilize the expression of PFKFB3, and thus promote the glycolysis of KFs and the progression of keloid, implying that SPARC/p38γ/PFKFB3 signaling axis may be a new molecular mechanism in the therapy of keloids." (PMID 39482755, 2024). "Thus, we hypothesized that SPARC might regulate the p38γ pathway to stabilize the expression of PFKFB3 protein, thereby participating in the glycolysis of KFs and keloid progression." (PMID 39482755, 2024). "Our findings verified that SPARC could activate p38γ pathway to stabilize the expression of 6-phosphofructo-2-kinase/fructose-2,6-biphosphatase 3 (PFKFB3), and thus participate in the glycolysis of keloid fibroblasts and the progression of keloid." (PMID 39482755, 2024).
kidney injury (2 papers, 2021 to 2023). Trauma to the kidney. "Taken together, these findings indicated that the activation of PFKFB3 played an important role in mitochondrial fitness and dysfunctional mitochondria elimination after kidney injury." (PMID 33634980, 2021).
lymph node metastasis (2 papers, 2022 to 2023). "Moreover, high PFKFB3 expression was associated with poor DFI and DSS in patients with OSCC with lymph node metastasis." (PMID 37919747, 2023).
malignant glioma (2 papers, 2021 to 2024). A grade III or grade IV glioma arising from the central nervous system. "Previously, we have shown that the PFKFB3 splice pattern is notably different between healthy brain tissue and rapidly proliferating malignant gliomas." (PMID 34234350, 2021).
metastatic tumors (2 papers, 2019 to 2024). "PFKFB3 blockade therapy also improves chemotherapy for primary and metastatic tumors." (PMID 39729352, 2024). "Indeed, Pfkfb3 expression was significantly elevated (by 4–8-fold) in metastatic tumors relative to their dormant counterparts." (PMID 31413316, 2019).
ovarian tumors (2 papers, 2015 to 2022). "In addition, 13 pairs of FFPE tissue sections composed of metastatic foci and matched primary ovarian tumors were examined through PFKFB3 staining with IHC." (PMID 35155224, 2022).
overnutrition (2 papers, 2016 to 2023). An imbalanced nutritional status resulting from excessive intake of nutrients. "To gain nutritional insight into PFKFB3 regulation, we examined the direct effects of glucose and palmitate, two major macronutrients associated with overnutrition, on IEC responses." (PMID 27387960, 2016). "Recent studies have reported that PFKFB3 regulates inflammation induced by a high-fat diet (HFD) and inflammation associated with overnutrition." (PMID 37762634, 2023).
pancreatic adenocarcinoma (2 papers, 2019 to 2023). "Although the overexpressed PFKFB3/4 isoenzymes are considered oncogenic, mantle cell lymphoma, ovarian and pancreatic adenocarcinoma data sets have revealed that patients with low expression of PFKFB3 enzyme have significantly worse survival rates in comparison to the ones with high expression." (PMID 31754349, 2019). "Furthermore, strong correlations between PFKFB3 expression and pathological stage were observed in endocervical adenocarcinoma (CESC), THCA, pancreatic adenocarcinoma (PAAD), testicular germ cell tumors (TGCT), and Ovarian serous cystadenocarcinoma (OV, all P < 0.05)." (PMID 37253634, 2023).
prediabetes (2 papers, 2022 to 2024). "The fact that the HIF1α and PFKFB3 upregulation and the loss of β-cell function happen concomitantly in prediabetes implicates further the inhibition of β-cell fitness competition at the early β-cell decompensation stage." (PMID 35318430, 2022). "Because PFKFB3-positive “loser” β-cells are long-lived cells carried on from prediabetes, we asked about the mechanism by which PFKFB3 can exert protection despite the global distortion of RiBi and mitochondrial respiration." (PMID 39313296, 2024).
rhabdomyosarcoma (2 papers, 2019 to 2020). A rare aggressive malignant mesenchymal neoplasm arising from skeletal muscle. "The siRNA transfection of the EV-A71-susceptible human rhabdomyosarcoma (RD) cells suppressed the PFKFB3 transcript for around 80%." (PMID 32717953, 2020).
small cell lung carcinoma (2 papers, 2022 to 2023). Small cell lung cancer (SCLC) is a highly aggressive malignant neoplasm, accounting for 10-15% of lung cancer cases, characterized byrapid growth, and early metastasis. "In small-cell lung carcinoma cell lines PFKFB3 inhibition attenuated invasion/migration by downregulating YAP/TAZ signalling." (PMID 37689702, 2023). "Inhibition of PFKFB3 by the glycolytic inhibitor PFK158 and by shRNA stable knockdown in small cell lung carcinoma (SCLC) cell lines inhibited glycolysis, proliferation, spheroid formation, and the expression of cancer stem cell markers CD133, Aldh1, CD44, Sox2, and ABCG2." (PMID 35804016, 2022).
steatosis (2 papers, 2021 to 2025). Increased lipid within the cytoplasm of cells. "Our data indicated that the beneficial effects of IL‐22 on HFD‐induced renal injury, necrosis, steatosis, mitochondrial dysfunction, and ROS accumulation and the activation of related signaling pathways were significantly blocked by PFKFB3 knockdown." (PMID 33634980, 2021).
Stroke (2 papers, 2019 to 2025). Sudden impairment of blood flow to a part of the brain due to occlusion or rupture of an artery to the brain. "Glycolytic metabolic processes, particularly enzymes like HK2, PFKFB3, PKM2, PDH, LHD, and metabolites such as lactate, have emerged as potential predictors of stroke risk, development, and prognosis." (PMID 39926015, 2025). "Notch signaling pathway (closely related to angiogenesis) can be activated by PFKFB3 to promote the formation of brain microvascular endothelial cells (BMECs) after stroke." (PMID 39926015, 2025).
thyroid tumor (2 papers, 2021 to 2025). A benign or malignant neoplasm affecting the thyroid gland. "Another member of this family, PFKFB3, is frequently over-expressed in many human tumors, including lung, breast, colon, pancreas, ovary, pancreas and thyroid tumors, but under-expressed in normal tissues, so targeting PFKFB3 to treat cancer has become an attractive strategy." (PMID 41000074, 2025).
Ureteral obstruction (2 papers, 2023 to 2025). Obstruction of the flow of urine through the ureter. "The expression of PFKFB3 is significantly elevated in the renal tissues of mice following unilateral ureteral obstruction (UUO) or ischemia/reperfusion (I/R) injury, suggesting a critical role for PFKFB3 in the pathogenesis of kidney fibrosis." (PMID 40271532, 2025).
alcohol- (1 paper, 2024). "In summary, our data show that KO of Pfkfb3 abrogates tissue injury in alcohol-related AP by attenuating Ca2+ overload in pancreatic acinar cells." (PMID 38781030, 2024). "Dysregulated calcium signaling is the nexus event for AP progression, and disruption of the PFKFB3-IP3R interaction resulted in a reduction in calcium signaling, which explains the protective effect of Pfkfb3 KO in alcohol-related AP." (PMID 38781030, 2024). "Furthermore, we defined an interaction between PFKFB3 and IP3R, a key early regulator of AP development and progression, and proposed that PFKFB3 promotes of severity of alcohol-related AP by upregulating intracellular calcium levels in an IP3R-dependent manner." (PMID 38781030, 2024).
amyloid (1 paper, 2023). "For instance, PFKFB3 was downregulated in amyloid-related microglia, but not in tau-related microglia." (PMID 37833292, 2023).
benign intestinal neoplasms (1 paper, 2025). "Notably, benign intestinal neoplasms exhibited a significantly higher density of PFKFB3+ cells within the stroma compared to CRC tissues (86.32 ± 35.54 vs. 30.19 ± 25.33, p < 0.00001)." (PMID 41516095, 2025).
bladder tumour (1 paper, 2025). "We found that seven of these genes, IGFBP3, VEGF, CCNG2, NDRG1, PFKFB3, ADM and SLC2A1, were also upregulated in MIBC and/or NMIBC in our study, suggesting parallel hypoxia-induced expression changes with primary bladder tumour tissue." (PMID 40867253, 2025).
brain injury (1 paper, 2025). Acute and chronic (see also brain INJURIES, CHRONIC) injuries to the brain, including the cerebral hemispheres, CEREBELLUM, and brain STEM. "Ischemic brain injury can be ameliorated by knockdown or inhibition of PFKFB3 is able to block MDSC differentiation and increase endogenous MDSCs, thereby suppressing the activation state of T effector cell subpopulations." (PMID 39926015, 2025). "It was found that downregulation of PFKFB3-driven glycolysis partially reduced lactate-mediated activation of mTORC1, thereby inhibiting MDSC differentiation to mature inflammatory cells to attenuate acute ischemic brain injury." (PMID 39926015, 2025).
celiac disease (1 paper, 2016). An autoimmune genetic disorder with an unknown pattern of inheritance that primarily affects the digestive tract. "A nearby gene in this region is PFKFB3, which was previously shown to be associated with celiac disease." (PMID 27015091, 2016). "One SNP (rs117139146) located in the intragenic region of chromosome 10p15 encoding for PFKFB3 (6-phosphofructo-2-kinase/fructose-2,6-biphosphatase 3) was initially identified as being associated with celiac disease through the 1000 Genomes Project using the ImmunoChip in 2012." (PMID 27015091, 2016). "In a meta-analysis of Dutch and UK data sets, shared association with this PFKFB3/PRKCQ region was observed in both RA and celiac disease." (PMID 27015091, 2016).
cervical squamous cell carcinoma (1 paper, 2019). A squamous cell carcinoma arising from the cervical epithelium. "Interestingly, in cervical squamous cell carcinoma we revealed that patients with high expression of both, PFKFB3 and PFKFB4 have significantly worse overall survival in comparison to the ones with low expression." (PMID 31754349, 2019).
chronic heart failure (1 paper, 2023). "In conclusion, 3PO effectively reduced fibrosis and improved adverse cardiac remodeling after MI, suggesting PFKFB3 inhibition as a novel therapeutic strategy to reduce the incidence of chronic heart failure following MI." (PMID 37509108, 2023).
CLN7 disease (1 paper, 2022). "Here the authors report that in a mouse model of CLN7 disease neuronal reactive oxygen species and the activity of glycolytic enzyme PFKFB3 are increased, while PFKFB3 inhibition ameliorates hallmarks of pathology." (PMID 35087090, 2022).